SYP (synaptophysin)
Diseases named in the same sentence as SYP in open-access papers (continued):
Sharing a sentence is not in itself a finding about the gene and the disease.
Cushing syndrome (1 paper, 2023). Cushing's syndrome (CS) encompasses a group of hormonal disorders caused by prolonged and high exposure levels to glucocorticoids that can be of either endogenous (adrenal cortex production) or exogenous (iatrogenic) origin. "Immunohistochemically, all tumors were diffusely positive for CK18 and synaptophysin, while chromogranin A was diffusely expressed in both Cushing syndrome-associated RenNETs and in 3/11 non-functioning RenNETs." (PMID 37405461, 2023).
delirium (1 paper, 2020). A disorder characterized by confusion; inattentiveness; disorientation; illusions; hallucinations; agitation; and in some instances autonomic nervous system overactivity. "The anesthesia/surgery induced greater postoperative delirium-like behavior, increased brain IL-6 levels, decreased PSD-95 and synaptophysin levels, and mitochondrial dysfunction in 18 than 9 months old mice." (PMID 31974315, 2020). "The postoperative delirium-like behavior, gut microbiota, levels of brain IL-6, PSD-95 and synaptophysin, and mitochondrial function were determined by a battery of behavioral tests, 16s rRNA sequencing, ELISA, Western blot and Seahorse XFp Extracellular Flux Analyzer." (PMID 31974315, 2020).
demyelination (1 paper, 2025). "Temporal variability in marker sensitivity may also be relevant, as demonstrated in a pharmacologically induced murine demyelination model in which nNF-positive axonal bulbs were detected during the acute phase of disease, while β-APP and synaptophysin became more prominent at later time points." (PMID 40733579, 2025).
diffuse midline glioma (1 paper, 2025). A diffuse glioma that arises from the midline structures of the central nervous system. "In contrast, diffuse midline gliomas (DMGs) typically lack significant synaptophysin expression." (PMID 40937216, 2025).
Down syndrome (1 paper, 2014). "Work in hippocampal cell culture, under toxic conditions, and in male Ts65Dn mice (model of Down Syndrome) also shows that fluoxetine can rescue or improve synaptophysin expression." (PMID 24757568, 2014).
ductal carcinoma (1 paper, 2021). "The present case was histologically confirmed as ductal carcinoma with neuroendocrine differentiation, showing positivity for synaptophysin and focal positivity for neuron-specific enolase." (PMID 33692758, 2021).
duodenal tumor (1 paper, 2017). "The cancer cells in the duodenal tumor and lymph node both expressed the epithelial marker CDX2, as well as the neuroendocrine markers CD56, and synaptophysin, indicating that the metastasis originated from the duodenal tumor." (PMID 28881081, 2017).
embryonal rhabdomyosarcoma (1 paper, 2016). A poorly circumscribed morphologic variant of rhabdomyosarcoma. "An ultrasound-guided biopsy showed embryonal rhabdomyosarcoma on histology and immunohistochemistry, with strong positivity of neural cell adhesion molecule and myogenin while results for cytokeratin AE1/AE3, cluster of differentiation 45, synaptophysin, and chromogranin were negative." (PMID 27998313, 2016).
endolymphatic sac tumor (1 paper, 2012). An aggressive epithelial neoplasm arising from the temporal bone. "Typical Zellballen pattern along with immunopositive for chromogranin and synaptophysin distinguishes it from Endolymphatic sac tumor." (PMID 22953101, 2012).
endometrial carcinoma (1 paper, 2010). A malignant tumor arising from the epithelium that lines the cavity of the uterine body. "The immunoexpression of synaptophysin has previously been described in undifferentiated endometrial carcinomas where it did not seem to have a significant prognostic potential." (PMID 20462442, 2010).
esophageal NETs (1 paper, 2014). "In this study, we performed survival analysis for esophageal NETs, but synaptophysin and chromogranin were not prognostic factors." (PMID 25098730, 2014).
esophageal small-cell carcinomas (1 paper, 2021). "Synaptophysin immunoreactivity was detected in all esophageal small-cell carcinomas, whereas chromogranin A was expressed in 10 (67%) esophageal small-cell carcinomas." (PMID 32556556, 2021).
esophageal tumor (1 paper, 2025). "In this case, the esophageal tumor’s immunophenotype was consistent with previously reported cases and also expressed synaptophysin with a Ki-67 index below 10%." (PMID 40441262, 2025).
fibromyalgia (1 paper, 2026). A chronic disorder of unknown etiology characterized by pain, stiffness, and tenderness in the muscles of neck, shoulders, back, hips, arms, and legs. "Fibromyalgia pain was associated with enhanced glutamatergic transmission, as shown by immunohistochemical assessment of synaptophysin and PSD95 in the DRG along with VGLUT, PSD95, NMDA, NMDA receptor 2B, and AMPA in the spinal cord." (PMID 41686296, 2026).
gangliocytoma (1 paper, 2025). A well differentiated, slow growing neuroepithelial neoplasm composed of neoplastic, mature ganglion cells. "Histopathology revealed a biphasic tumor composed of small monomorphic nests and solid sheets of pitNET cells (synaptophysin and chromogranin A positive, S100 negative) and large voluminous eosinophilic cells of the gangliocytoma component (synaptophysin, chromogranin A and S100 positive)." (PMID 41522407, 2025).
gastric neuroendocrine neoplasm (1 paper, 2025). A neoplasm with neuroendocrine differentiation that arises from the stomach. "Gastric neuroendocrine neoplasms typically exhibit positive immunohistochemical staining for chromogranin A, synaptophysin, and INSM-1." (PMID 40248085, 2025).
glucocorticoid deficiency (1 paper, 2012). "Against this background, and together with the fact that both hippocampal synapsin and synaptophysin are known to be upregulated by glucocorticoids, we speculate that the long-term SV protein downregulation observed in our PTSD mouse model might result from trauma-induced glucocorticoid deficiency." (PMID 22900032, 2012).
hemangioendothelioma (1 paper, 2021). A vascular proliferation characterized by the presence of prominent endothelial cells and the formation of vascular channels. "Histologic examination showed a complex combination of epithelioid and retiform hemangioendothelioma areas which were positive for anti-synaptophysin staining." (PMID 34837560, 2021).
Hirschsprung disease (1 paper, 2019). Hirschsprung disease (HSCR) is a congenital intestinal motility disorder that is characterized by signs of intestinal obstruction due to the presence of an aganglionic segment of variable extent in the terminal part of the colon. "Two new markers, NSE and synaptophysin, have been extensively used for diagnosis of Hirschsprung’s disease." (PMID 30866930, 2019).
Hodgkins lymphoma (1 paper, 2022). A heterogeneous group of malignant lymphoid neoplasms of B-cell origin characterized histologically by the presence of Hodgkin and Reed-Sternberg (HRS) cells in the vast majority of cases. "There are caveats associated with the use of synaptophysin expression for the diagnosis of classic Hodgkin lymphoma." (PMID 36401284, 2022). "Follow-up studies on the mechanism underlying the expression of synaptophysin would also facilitate the diagnosis and understanding of Hodgkin lymphoma." (PMID 36401284, 2022). "Therefore, this study aims to determine the usefulness of synaptophysin as a diagnostic marker by investigating the frequency of synaptophysin expression in Hodgkin lymphoma." (PMID 36401284, 2022). "During the diagnosis of a case of Hodgkin lymphoma, we discovered that tumor cells stained positive for anti-synaptophysin antibodies." (PMID 36401284, 2022). "Our study showed that aberrant synaptophysin expression in classic Hodgkin lymphoma is an unexpectedly frequent finding." (PMID 36401284, 2022). "More extensive studies are needed to ascertain whether proteins such as restin, as well as synaptophysin, are expressed in other hematolymphoid tumors, and follow-up studies on the mechanisms underlying synaptophysin expression will facilitate the diagnosis and understanding of Hodgkin lymphoma." (PMID 36401284, 2022). "Of 59 classic Hodgkin lymphoma cases, 11 (19%) were positive for synaptophysin." (PMID 36401284, 2022). "Herein, we describe a novel finding of synaptophysin expression in Hodgkin lymphoma HRS cells." (PMID 36401284, 2022). "This experience prompted us to investigate synaptophysin expression in classic Hodgkin lymphoma." (PMID 36401284, 2022). "This index case led us to evaluate in synaptophysin expression in Hodgkin lymphoma." (PMID 36401284, 2022). "However, we experienced an index case of classic Hodgkin lymphoma with synaptophysin expression." (PMID 36401284, 2022). "Synaptophysin expression in Hodgkin lymphoma is a novel finding that has not been reported in the literature." (PMID 36401284, 2022). "Thus, if synaptophysin is positive along with CD30, it may help render a diagnosis of classic Hodgkin lymphoma." (PMID 36401284, 2022). "Chromogranin and CD56a were not expressed in the synaptophysin-positive classic Hodgkin lymphomas." (PMID 36401284, 2022). "However, it can be a diagnostic pitfall if the pathologist does not consider the possibility of a classic Hodgkin lymphoma in an unusual clinical setting or if synaptophysin staining was performed initially when the amount of diagnostic tissue was very small." (PMID 36401284, 2022).
Hydrocephalus (1 paper, 2022). Hydrocephalus is an active distension of the ventricular system of the brain resulting from inadequate passage of CSF from its point of production within the cerebral ventricles to its point of absorption into the systemic circulation. "Western blot analyses show that hydrocephalus, both acute and chronic, significantly reduced the expressions of the presynaptic marker protein synaptophysin and the glutamatergic presynaptic marker VGLUT1 in the striatum (n = 5–10)." (PMID 36437472, 2022).
Hyperreflexia (1 paper, 2019). Hyperreflexia is the presence of hyperactive stretch reflexes of the muscles. "In order to explore the specific mechanism by which therapeutic interventions alleviate hyperreflexia in rats, we used immunofluorescence colocalization to study the changes in the number and morphology of motor neurons and the surrounding SYP in the lumbar spinal cord segment." (PMID 30984254, 2019).
large cell medulloblastoma (1 paper, 2014). A medulloblastoma composed of large cells with prominent nucleoli and a larger amount of cytoplasm in contrast with the cells of the classic medulloblastoma. "Speckled synaptophysin is a typical feature found in large cell medulloblastomas." (PMID 24791927, 2014).
Leber congenital amaurosis (1 paper, 2016). Leber congenital amaurosis (LCA) is a retinal dystrophy defined by blindness and responses to electrophysiological stimulation (Ganzfeld electroretinogram (ERG)) below threshold, associated with severe visual impairment within the first year of life. "Immunohistochemical assays of the epithelial membrane antigen (EMA), S100, vimentin, KI67, creatine kinase (CK), Leber congenital amaurosis (LCA), CD68, antibodies against glial fibrillary acidic protein (GFAP), BCL2, anaplastic lymphoma kinase (ALK), and synaptophysin levels were performed." (PMID 27917338, 2016).
liver cirrhosis (1 paper, 2016). "In this study, there was a significant decrease in relative expression of hippocampal synaptophysin after induction of liver cirrhosis." (PMID 28337098, 2016).
lung NETs (1 paper, 2021). "In a large study of 345 primary lung neoplasms, INSM1 was found to have a specificity for lung NETs (97%) which is similar to CGA (98%), but greater than CD56 (87%) and SYP (90%)." (PMID 34943408, 2021).
lupus (1 paper, 2022). "We found that antibodies against synaptophysin and PSD-95 coimmunoprecipitated more C1q from lupus mouse hippocampal lysates (although with interanimal variability) than control mice." (PMID 35177587, 2022).
meningioma (1 paper, 2026). A generally slow growing tumor attached to the dura mater. "We aimed to explore neuroendocrine differentiation in meningiomas by investigating the following neuroendocrine markers: neural cell adhesion molecule (CD56/NCAM), chromogranin A, chromogranin B, chromogranin C, neuron-specific enolase (NSE), secretagogin, and synaptophysin." (PMID 41769706, 2026). "Our study does not support the hypothesis of neuroendocrine differentiation in meningiomas, as chromogranin A and synaptophysin were mostly absent." (PMID 41769706, 2026).
metastatic melanoma (1 paper, 2021). A melanoma that has spread from its primary site to another anatomic site. "Further tumor immunohistochemistry revealed extensive neuroendocrine differentiation with CD56, synaptophysin, and INSM1, as well as strong immunoreactivity for melanocyte markers including SOX10, S100, PRAME, and MITF, consistent with metastatic melanoma with neuroendocrine differentiation." (PMID 34926265, 2021).
migraine (1 paper, 2023). "In the hippocampus of migraine mice, we detected a significant downregulation of both APMAR (especially GluR1) and SYP, implying a downregulation of presynaptic function and synaptic scaling at this site." (PMID 36831874, 2023).
neuritis (1 paper, 2015). A neuropathy arising from inflammation of one or more nerves. "Dendrite outgrowth evaluation and semiquantification of the synaptophysin signal were performed on 3D reconstructed neuritis for each different treatment condition." (PMID 26510963, 2015).
papillary carcinoma (1 paper, 2025). A malignant epithelial neoplasm characterized by a papillary growth pattern. "Our patient also had a central compartment neck node that showed tumor deposits from medullary and papillary carcinoma, which was confirmed by immunohistochemistry (CK19 strongly positive, CD56 faint positivity, and synaptophysin positive)." (PMID 40677447, 2025).
pineal tumors (1 paper, 2009). "Of these pineal parenchymal tumors, 12 of 13 demonstrated immunoreactivity for synaptophysin, currently the most widely used marker of pineal tumors, in >75% of tumor cells and 12 of 13 demonstrated immunoreactivity for GFAP, a glial marker, in <5% of tumor cells." (PMID 19936203, 2009).
pineocytoma (1 paper, 2025). "Pineocytomas are composed of well-differentiated pinealocyte-like cells forming pineocytomatous rosettes with strong synaptophysin and neurofilament staining." (PMID 40585941, 2025). "In this case, histopathology confirmed both tumors, with synaptophysin and NSE positivity in the pineocytoma component and GFAP and OLIG2 positivity in the PA component; both showed a low proliferation index (Ki67 < 1%)." (PMID 40585941, 2025).
pituitary tumor (1 paper, 2025). A benign or malignant neoplasm affecting the pituitary gland. "Immunohistochemical staining of the pituitary tumor demonstrated positive for ACTH, chromogranin A, and synaptophysin, with Ki-67 index at 3%." (PMID 40213016, 2025).
placental insufficiency (1 paper, 2019). Failure of the placenta to deliver an adequate supply of nutrients and oxygen to the fetus. "Additionally, the protein level of synaptophysin has been reported to be reduced in the hippocampus of FGR animals on P35 using a utero-placental insufficiency model." (PMID 30659198, 2019).
prediabetes (1 paper, 2020). "Our result showing decreased synaptophysin expression in the myenteric plexus in HFD-Veh mice indicates that abnormal production and transport of synaptic neurotransmitters may underlie the neuronal functional impairment in prediabetes." (PMID 32704004, 2020).
primary progressive multiple sclerosis (1 paper, 2019). A multiple sclerosis that is characterized by steady worsening of neurologic functioning, without any distinct relapses or periods of remission. "Initial autopsy studies of patients with relapsing-remitting multiple sclerosis, primary progressive multiple sclerosis, and secondary progressive multiple sclerosis have reported decreased levels of synaptic proteins, including synaptotagmin and synaptophysin." (PMID 30582321, 2019).
rectal NETs (1 paper, 2016). "All G1 and G2 NETs were positive for synaptophysin while rectal NETs and G3 NETs were negative for chromogranin." (PMID 26684240, 2016).
retinal detachment (1 paper, 2020). An eye emergency condition which may lead to blindness if left untreated. "In the retina, pathogenic conditions such as retinal detachment and retinal inflammation caused the reduction of synaptophysin expression." (PMID 32872333, 2020).
seminoma (1 paper, 2013). A radiosensitive malignant germ cell tumor found in the testis (especially undescended), and extragonadal sites (anterior mediastinum and pineal gland). "The stain was negative for AE1 and AE3, epithelial tumor markers, PLAP, which excluded the hypothesis of seminoma, CD30, a marker of embrionary carcinoma and also chromogranin or synaptophysin." (PMID 23388220, 2013).
Senile plaques (1 paper, 2017). Senile plaques are extracellular deposits of amyloid in the gray matter of the brain. "What's more, previous studies showed that the reduction of the levels of synaptophysin, PSD-93 and PSD-95 occurred before the formation of senile plaques in mice with AD." (PMID 29190943, 2017).
serous carcinoma (1 paper, 2020).
stress-related disorder (1 paper, 2024). Stress-related disorders are mental health disorders that are a result of an atypical response to both short and long-term anxiety due to physical, mental, or emotional stress. "While citalopram primarily enhances serotonin availability, JSO appears to influence both neuroinflammation and neuroplasticity, as indicated by its effects on BDNF and synaptic proteins, such as PSD-95 and SYP, which are crucial for synaptic health and resilience in stress-related disorders." (PMID 39555096, 2024).
thoracic tumors (1 paper, 2021). "Staining a combination of synaptophysin, chromogranin and CD56 is currently advised to establish evidence of neuroendocrine differentiation in thoracic tumors." (PMID 33933015, 2021).
Thrombocytopenia (1 paper, 2025). A reduction in the number of circulating thrombocytes. "In particular, the expression of TAG1 (−1.33, −0.12; p ≤ 0.01), SYP (1.67, −0.44; p ≤ 0.03), UBC9 (1.9, −0.51; p ≤ 0.01), NAE1 (−1.18, 0.04; p ≤ 0.03) was altered in newborns with thrombocytopenia." (PMID 40003962, 2025).
tubular adenocarcinoma (1 paper, 2016). An infiltrating adenocarcinoma in which the malignant cells form tubular structures. "The proximal to the cardial lesion showed neuroendocrine morphology and immunoreactivity for synaptophysin, and the other a moderated tubular adenocarcinoma Borrmann type III." (PMID 26913067, 2016).
vulvar sarcoma (1 paper, 2020). "EMC is an extremely rare subtype of vulvar sarcoma that is consistently positive for vimentin, variable positivity for S100 protein, neuron-specific enolase and synaptophysin, completely negative for CK, and harhor EWSR1-NR4A3 fusion in about 65% of cases." (PMID 31915021, 2020).